FBXW7 (F-box and WD repeat domain containing 7)
Diseases named in the same sentence as FBXW7 in open-access papers (continued):
Sharing a sentence is not in itself a finding about the gene and the disease.
Granuloma (1 paper, 2022). A compact, organized collection of mature mononuclear phagocytes, which may be but is not necessarily accompanied by accessory features such as necrosis. "Immunohistochemistry stain demonstrated that FBXW7 was extensively expressed in the multinuclear giant cells of the granulomas of rabbits and humans and the multinuclear giant cells in the regions with inflammatory cells infiltrating those of the mouse." (PMID 35651754, 2022). "Moreover, there is a seemingly contradictory point between the negative regulation of FBXW7 on TNF-α vs FBXW7-mediated granulomas formation in this study." (PMID 35651754, 2022).
H1N1 virus infection (1 paper, 2017). "To further confirm the function of FBXW7 in vitro, we silenced FBXW7 in peritoneal macrophages with siRNA and detected the decreased expression of IFN-α4, IFN-β mRNA in FBXW7-silenced peritoneal macrophages upon VSV or H1N1 virus infection." (PMID 28287082, 2017).
hamartoma (1 paper, 2025). A benign and excessive tumor-like growth of mature cells and normal tissues which grow in a disorganized pattern. "Previous studies showed that the deletion of Fbxw7 in the liver leads to abnormal proliferation of the biliary system and the development of hamartomas, we wondered whether RPAP2 plays a causal role in this process." (PMID 39932049, 2025). "Although FBXW7 deprivation in the mouse liver induces abnormal proliferation of the biliary system and the development of hamartomas, the specific substrate(s) of FBXW7 responsible for this phenotype remain elusive." (PMID 39932049, 2025).
hemangioma (1 paper, 2024). A benign vascular lesion characterized by the formation of capillary-sized or cavernous vascular channels. "In conclusion, this paper reports a rare case of DEDHIL with phenotypic features such as hypertonia, labial hemangioma, hydrocele, and overgrowth that implies heterogeneity of FBXW7 gene-associated disorders and provides an example of a clinical diagnosis for specialists." (PMID 39364007, 2024). "Therefore, FBXW7 mutations may play an important role in the formation of hemangiomas." (PMID 39364007, 2024).
infantile hemangiomas (1 paper, 2024). "The exact pathogenesis of infantile hemangiomas is unknown; however, several studies have identified FBXW7 as a positive angiogenesis regulator that counteracts Notch activity in the vascular endothelium." (PMID 39364007, 2024).
Infertility (1 paper, 2024). "To explore whether the infertility in Fbxw7 OcKO mice resulted from progressive follicle loss, we conducted histological analyses of ovaries." (PMID 39031722, 2024).
intrahepatic cholangiocarcinoma (1 paper, 2019). A carcinoma that arises from the intrahepatic bile duct epithelium in any site of the intrahepatic biliary tree. "In intrahepatic cholangiocarcinoma (IHCC), FBXW7 downregulation is directly linked with lymph nodes metastasis and poorer prognosis with 3 years survival rates of 29.4% than those with high expression of FBXW7 with 3 years survival rates of 72.7%." (PMID 30791487, 2019).
invasive carcinoma (1 paper, 2016). A carcinoma that is not confined to the epithelium, and has spread to the surrounding stroma. "The expression of FBXW7 and substrates were studied in 296 invasive carcinomas by immunohistochemistry and disease-free survival was analyzed in a subset of patients treated with paclitaxel." (PMID 27409838, 2016).
knee osteoarthritis (1 paper, 2023). "In knee osteoarthritis, mechanical overloading has been reported to downregulate F-box and WD repeat domain containing 7 (FBXW7) ubiquitin ligase and activate the JNK pathway, therefore promoting chondrocyte senescence." (PMID 37016437, 2023).
laryngeal carcinoma (1 paper, 2023). Carcinoma that arises from the laryngeal epithelium. "LncRNA-MIR22HG regulates the expression of FBXW7 in the laryngeal cancer cells by competitively binding of miR-5000-3p, erasing its expression." (PMID 36998461, 2023). "Finally, decreased expression of miR-5000-3p inhibited the proliferation and migration of laryngeal cancer cells, while upregulation of MIR22HG expression led to an increase in FBXW7 expression and protein level." (PMID 36998461, 2023).
Lewis lung carcinoma (1 paper, 2020). "We identified a significant increase in the proportion of M2-like TAMs and aggravated tumor growth in mice with myeloid FBXW7 deficiency by subcutaneous inoculation with Lewis lung carcinoma cells (LLCs)." (PMID 33260160, 2020). "We found that myeloid cell-specific FBXW7-deficient (Lysm+FBXW7f/f) C57BL/6 mice showed exacerbated tumor progression and had a higher proportion of M2-like TAMs in solid tumor tissues after the subcutaneous injection of Lewis lung carcinoma cells (LLCs)." (PMID 33260160, 2020).
liver failure (1 paper, 2020). A liver disease characterized by the liver losing or has lost all of its function. "Then, FBXW7 was a suppressor of septic liver failure in LPS‐induced mice; overexpression of FBXW7 could significantly attenuate LPS‐induced liver failure in mice." (PMID 32369227, 2020).
meningioma (1 paper, 2020). A generally slow growing tumor attached to the dura mater. "We also observed an enrichment in alterations in CDKN2A/B, KDM6A, ARID1A, PTEN, FBXW7, and SUFU in comparison with NF2-wt meningiomas." (PMID 33087175, 2020).
Mm (1 paper, 2022). "To investigate whether FBXW7 regulates the NF-κB signaling pathway, we utilized an immunofluorescent assay to observe the interaction between FBXW7 and NF-κBp65 along with Mm infection." (PMID 35651754, 2022).
mood disorder (1 paper, 2022). A cognitive disorder a disturbance in which the person's mood is hypothesized to be the main underlying feature. "Moreover, as explained in the Introduction, FBXW7 modulates some pathways that play a role in mood disorders, including neurogenesis, mTOR, DISC, and PGC-1α." (PMID 35055338, 2022).
mycobacterial infection (1 paper, 2022). "Taken together, our study uncovered a previously unknown role of FBXW7 in regulating TNF-α dynamics during mycobacterial infection, which provides new insights into understanding the role of FBXW7 in anti-tuberculosis immunity and its related clinical significance." (PMID 35651754, 2022).
nicotine addiction (1 paper, 2025). "The signaling pathways enriched by differential metabolites, such as the mToR signaling pathway, central carbon metabolism in cancer, pyrimidine metabolism, and nicotine addiction, indicate that FBXW7 may govern the incidence of CRC via these pathways." (PMID 39823500, 2025).
nonalcoholic steatohepatitis (1 paper, 2023). "NASH, nonalcoholic steatohepatitis, a severe fatty liver disease with no cure, can manifest through loss-of-function of the E3 ligase FBXW7." (PMID 37914694, 2023).
Osteochondroma (1 paper, 2021). A common, benign cartiliginous neoplasm arising from the metaphysis of bone. "It is possible that EXT1 is functionally associated with FBXW7, presumably through priming kinases and substrates like N1‐ICD and therefore, mutational events affecting the EXT1 or FBXW7 gene can significantly affect the pathogenesis in osteochondroma patients through the NOTCH pathway." (PMID 33822486, 2021). "Exostosin glycosyltransferase 1 (EXT1), an endoplasmic reticulum transmembrane protein that frequently mutated in multiple osteochondromas, acts as a connector between NOTCH1 and FBXW7." (PMID 33822486, 2021).
Osteopenia (1 paper, 2021). Osteopenia is a term to define bone density that is not normal but also not as low as osteoporosis. "Consistently, postnatal deletion of Fbxw7 in mice results in reduced bone formation and mild osteopenia in 3-month-old mice, due to reduced osteoblastogenesis." (PMID 34518642, 2021).
osteoporosis (1 paper, 2019). A condition of reduced bone mass, with decreased cortical thickness and a decrease in the number and size of the trabeculae of cancellous bone (but normal chemical composition), resulting in increased fracture incidence. "Based on previous studies, ATF2, FBXW7, and RDX were osteoporosis-related DEGs." (PMID 30809532, 2019).
ovarian tumor (1 paper, 2019).
papillary adenocarcinoma (1 paper, 2023). A morphologic variant of adenocarcinoma.
papilloma (1 paper, 2012). A benign epithelial neoplasm that projects above the surrounding epithelial surface and consists of villous or arborescent outgrowths of fibrovascular stroma. "Fbxw7 deletions were detected in some papillomas and in the majority of the carcinomas studied." (PMID 22348067, 2012).
penile cancer (1 paper, 2020). A primary or metastatic malignant neoplasm that affects the penis. "In addition, the miR-223-3p microRNA regulates the FBXW7 gene, which is a tumor suppressor, and is often mutated in several types of human cancers, including penile cancer in the advanced stage." (PMID 32102516, 2020).
polyposis (1 paper, 2014). "On an Apc mutant background, polyposis developed more rapidly in R482Q than Fbxw7+/− animals, and there was additionally a relative shift in polyp numbers to SB1, a feature previously associated with more severe disease." (PMID 23676439, 2014).
progeria (1 paper, 2023). "Interestingly, progeria‐specific mechanisms in the Aging map, involving SREBF1, GSK3A/B, and FBXW7, are related to PGC1A activity in the PD map, indicating potential cell and tissue specificity of the mechanism." (PMID 36648161, 2023).
rectum (1 paper, 2019).
renal fibrosis (1 paper, 2021). A final common manifestation of a wide variety of chronic kidney diseases characterized by glomerulosclerosis and tubulointerstitial fibrosis. "On this basis, we suggest that JMJD3 may also inhibit development of renal fibrosis by inactivation of the Notch signaling pathway through restriction of FBXW7 downregulation." (PMID 33456568, 2021).
rhabdomyosarcoma (1 paper, 2022). A rare aggressive malignant mesenchymal neoplasm arising from skeletal muscle. "Also, further studies on the discovered mutations in genes such as CTNNB1, BCOR, FBXW7, and others may provide targets for novel treatments in patients with rhabdomyosarcoma." (PMID 35530877, 2022).
Salmonella Infections (1 paper, 2022). Infections with bacteria of the genus SALMONELLA. "Although a previous study reported that FBXW7 was downregulated after Salmonella infection, the function of FBXW7 in the immune responses during bacterial infection is still unknown." (PMID 35651754, 2022).
steatosis (1 paper, 2019). Increased lipid within the cytoplasm of cells. "Moreover, liver-specific Fbxw7 knockout causes enhancement of hepatic lipogenesis and steatosis in mice." (PMID 31215394, 2019).
tauopathies (1 paper, 2025). "The reduction in FBXW7 in the brains of AD patients and the tauopathy mouse models implicates an involvement of FBXW7 in the pathogenesis of tauopathy." (PMID 41311387, 2025). "We demonstrated that sorafenib can significantly ameliorate cognitive deficits and tau pathologies in PS19 tauopathy model mice through multiple mechanisms, including promoting the E3 ubiquitin ligase FBXW7 to facilitate the degradation of tau and phosphorylated tau." (PMID 41311387, 2025). "Finally, we showed that FBXW7 expression decreased in the brains of AD patients and tauopathy model mice, and that overexpression of FBXW7 in the hippocampus attenuated cognitive deficits and tau pathologies in PS19 mice." (PMID 41311387, 2025). "Moreover, we revealed that FBXW7 expression decreases in tauopathies, and restoring its levels may provide an alternative strategy for disease intervention." (PMID 41311387, 2025).
thymic carcinoma (1 paper, 2022). Thymic carcinoma (TC) is a type of thymic epithelial neoplasm characterized by a high malignant potential.
tongue squamous cell carcinoma (1 paper, 2020). A squamous cell carcinoma that arises from the tongue. "In tongue squamous cell carcinoma, miR-24 promoted its proliferation, migration and invasion through targeting FBXW7 (F-box and WD repeat domain containing 7)." (PMID 33123467, 2020).
tonsil (1 paper, 2023).
uterine tumors (1 paper, 2024).
tumor (618 papers, 2007 to 2026). "As with the p.I35S mutations in Ctnnb1, this suggests that subsequent loss of Fbxw7 promotes tumour formation by a subset of transformants with existing N-terminal truncations of APC." (PMID 41339549, 2026). "In a variety of tumors such as colorectal cancer and breast cancer, mutations or downregulation of the FBXW7 gene lead to abnormal accumulation of oncogene proteins, promoting tumor initiation and progression." (PMID 40534867, 2025). "Mechanistically, Fbxw7 intervenes in the polarization of M2-like tumor-associated macrophages by orchestrating c-Myc's degradation." (PMID 40034124, 2025). "The FBXW7 gene is recognized as a tumor suppressor in human cancers, with decreased expression of FBXW7 being associated with unfavorable clinicopathological characteristics." (PMID 40034124, 2025). "For instance, FBXW7, a well-characterized tumor suppressor, is frequently mutated or downregulated in cancers, leading to the accumulation of oncogenic substrates like c-Myc and Cyclin E, thereby driving tumor progression." (PMID 40534867, 2025). "Acting as a tumor suppressor, FBXW7 is expressed in three isoforms (α, β, γ), encoded by a single locus on chromosome 4q32 and is pivotal in maintaining cellular homeostasis and genomic stability." (PMID 41373479, 2025). "FBXW7 loss-of-function produces complex, context-dependent effects: it can promote tumor aggressiveness by stabilizing oncogenic substrates (e.g., Cyclin E, EGFR) yet also generate pharmacologically exploitable vulnerabilities." (PMID 41373479, 2025). "High FBXW7 expression is associated with a “hot” tumor microenvironment, which exhibits a more favorable response to PD-1 blockade therapy, highlighting FBXW7 as a potential biomarker for immunotherapy efficacy." (PMID 40534867, 2025). "As a well-known tumor suppressor, FBXW7 is frequently inactivated or loss of expression in a wide array of human cancers." (PMID 38454442, 2024). "In this TN tumor, FBXW7 CNV loss occurred in concomitance with a splice-site variant in another E3 ubiquitin ligase gene, UBR5." (PMID 39208653, 2024). "FBXW7 participates in the polarization of tumor-associated macrophages through various pathways, thereby influencing tumor progression." (PMID 39748950, 2024). "FBXW7 is a known tumour suppressor, and its loss leads to cancer development due to the disruption of oncoproteins degradation and chromosome instability." (PMID 39340537, 2024). "demonstrate that loss of FBXW7 in tumour cells imparts a synthetic lethal effect with CDC7 inhibition." (PMID 37866880, 2024). "FBXW7 is the most recurrently mutated F‐box gene in human cancer, acting as a tumour suppressor, being commonly mutated, deleted or hypermethylated across cancer types, notably endometrial (~ 20%) and colorectal (17.5%) subtypes." (PMID 37866880, 2024). "Specifically, reduced FBXW7 mRNA expression in tumor tissues is inversely associated with CRC prognosis." (PMID 39749199, 2024). "The F‐box and WD repeat domain containing 7 (FBXW7) tumour suppressor gene encodes a substrate‐recognition subunit of Skp, cullin, F‐box (SCF)‐containing complexes." (PMID 37866880, 2024). "It is worth considering how the destructive effects of CSCs are caused by silencing FBXW7 and how its own tumor suppressor effects can be balanced." (PMID 38027013, 2023). "The strategies and challenges implicated in overcoming tumor therapy resistance by targeting FBXW7 are also discussed." (PMID 38027013, 2023). "Multiple cancer types acquire somatic mutations in the gene FBXW7, which encodes an F-box protein important for the degradation of tumor promoting proteins such as Cyclin E1, c-Myc, mTOR, Notch1 and SNAIL." (PMID 38155930, 2023). "Research in mouse models confirmed that FBXW7 deletion causes mammary epithelial cell degeneration with invasive cancer transformation and that the number of transplanted tumor nodules in the lungs of FBXW7 gene-deficient mice is significantly increased." (PMID 37658431, 2023).